SMARCC2 (SWI/SNF related BAF chromatin remodeling complex subunit C2)
Description:
Involved in transcriptional activation and repression of select genes by chromatin remodeling (alteration of DNA-nucleosome topology). Component of SWI/SNF chromatin remodeling complexes that carry out key enzymatic activities, changing chromatin structure by altering DNA-histone contacts within a nucleosome in an ATP-dependent manner. Can stimulate the ATPase activity of the catalytic subunit of these complexes. May be required for CoREST dependent repression of neuronal specific gene promoters in non-neuronal cells. Belongs to the neural progenitors-specific chromatin remodeling complex (npBAF complex) and the neuron-specific chromatin remodeling complex (nBAF complex). During neural development a switch from a stem/progenitor to a postmitotic chromatin remodeling mechanism occurs as neurons exit the cell cycle and become committed to their adult state. The transition from proliferating neural stem/progenitor cells to postmitotic neurons requires a switch in subunit composition of the npBAF and nBAF complexes. As neural progenitors exit mitosis and differentiate into neurons, npBAF complexes which contain ACTL6A/BAF53A and PHF10/BAF45A, are exchanged for homologous alternative ACTL6B/BAF53B and DPF1/BAF45B or DPF3/BAF45C subunits in neuron-specific complexes (nBAF). The npBAF complex is essential for the self-renewal/proliferative capacity of the multipotent neural stem cells. The nBAF complex along with CREST plays a role regulating the activity of genes essential for dendrite growth (By similarity). Critical regulator of myeloid differentiation, controlling granulocytopoiesis and the expression of genes involved in neutrophil granule formation (By similarity).
Synonyms: BAF170; Rsc8; CRACC2; CSS8
Tractability: Small molecule: a structure with a bound ligand is known. PROTAC: UniProt records ubiquitination sites on it; ubiquitination databases record sites on it; its protein half-life has been measured.
Gene: Protein-coding gene on chromosome 12 (56,162,359 to 56,189,567, reverse strand). Ensembl gene ENSG00000139613.
Subcellular location: Nucleus
Subcellular location (Human Protein Atlas): Nucleoplasm
Pathways (Reactome):
Chromatin organization: Formation of neuronal progenitor and neuronal BAF (npBAF and nBAF); Formation of the embryonic stem cell BAF (esBAF) complex; Formation of the non-canonical BAF (ncBAF) complex; Formation of the polybromo-BAF (pBAF) complex; RMTs methylate histone arginines
Gene expression (Transcription): RUNX1 interacts with co-factors whose precise effect on RUNX1 targets is not known; Regulation of endogenous retroelements by Piwi-interacting RNAs (piRNAs)
Developmental Biology: Regulation of MITF-M-dependent genes involved in pigmentation
Gene Ontology:
Molecular function: ATP-dependent chromatin remodeler activity; nucleosomal DNA binding; protein binding; histone binding; transcription coactivator activity
Biological process: chromatin remodeling; negative regulation of DNA-templated transcription; positive regulation of DNA-templated transcription; positive regulation of cell differentiation; positive regulation of double-strand break repair; positive regulation of myoblast differentiation; positive regulation of T cell differentiation; regulation of G0 to G1 transition; regulation of G1/S transition of mitotic cell cycle; regulation of mitotic metaphase/anaphase transition; regulation of nucleotide-excision repair; regulation of transcription by RNA polymerase II; nucleosome disassembly; regulation of DNA-templated transcription
Cellular component: chromatin; nucleoplasm; protein-containing complex; SWI/SNF complex; bBAF complex; brahma complex; kinetochore; nBAF complex; npBAF complex; nuclear matrix; RSC-type complex; nucleus
Genetic constraint (gnomAD): Loss-of-function variants: 12 observed, 116.62 expected, observed/expected ratio (o/e) 0.1, 90% interval 0.065 to 0.17. The upper end of that interval is the gene's LOEUF score, 0.17, which puts it in group 1 of 6, group 1 being the genes least tolerant of losing a copy. Missense variants: 926 observed, 1,425 expected, observed/expected ratio (o/e) 0.65, 90% interval 0.62 to 0.69. Synonymous variants: 532 observed, 554.36 expected, observed/expected ratio (o/e) 0.96, 90% interval 0.89 to 1.03.
Gene-disease validity (ClinGen):
ClinGen rates the evidence that SMARCC2 causes each of these diseases.
Coffin-Siris syndrome (autosomal dominant): Definitive. Coffin-Siris syndrome (CSS) is a rare congenital multi-systemic genetic disorder characterized by aplasia or hypoplasia of the distal phalanx or nail of the fifth digit, developmental delay, intellectual disability, coarse facial features, and other variable clinical manifestations.
Homologues: Orthologues: chimpanzee SMARCC2 (100% identical), macaque SMARCC2 (99% identical), rabbit SMARCC2 (96% identical), rat Smarcc2 (95% identical), pig SMARCC2 (94% identical), mouse Smarcc2 (94% identical), guinea pig SMARCC2 (93% identical), dog SMARCC2 (91% identical), tropical clawed frog smarcc2 (73% identical), zebrafish smarcc2 (65% identical). Paralogues in human: SMARCC1 (56% identical), MYSM1 (11% identical), MPND (7% identical).
Diseases named in the same sentence as SMARCC2 in open-access papers:
SMARCC2 is named in the same sentence as 59 diseases in open-access papers, as found by Europe PMC text mining. Sharing a sentence is not in itself a finding about the gene and the disease. The quoted sentences say what the papers report.
breast carcinoma (4 papers, 2011 to 2024). "For example, AC073896.4 is sense overlapping to gene SMARCC2, which is one of the core subunits of human SWI/SNF complex, which is known to be associated with breast cancer." (PMID 38838009, 2024). "Western blotting of PARP1 co-immunoprecipitated proteins confirmed the direct interaction of PARP1 with ARID1A and BRG1, but also with other subunits of SWI/SNF, such as SMARCC1 and SMARCC2, in the studied breast cancer cell lines." (PMID 31614656, 2019). "These included β-catenin-mediated transcription-related CALCOCO1, breast cancer poor-prognosis marker SBEM, and SMARCC2, a member of SWI/SNF chromatin-remodeling complex interacting with BRCA1." (PMID 21542898, 2011).
gastric cancer (4 papers, 2019 to 2023). A primary or metastatic malignant neoplasm involving the stomach. "Frameshift alterations in colorectal and gastric cancers have been reported to cause the early arrest of amino acid synthesis of SMARCC2 protein, similar to the typical loss of function mutations." (PMID 37516822, 2023).
autism (3 papers, 2023 to 2025). Persistent deficits in social interaction and communication and interaction as well as a markedly restricted repertoire of activity and interest as well as repetitive patterns of behavior. "Exactly how PAK1 activation controls brain development, and why specific chromatin remodeler components, e.g., BAF170 encoded by SMARCC2 in autism, await clarification." (PMID 37124926, 2023).
Coffin-Siris syndrome (3 papers, 2021 to 2026). "Recently, heterozygous variants in the SWI/SNF‐related, matrix‐associated, actin‐dependent regulator of chromatin subfamily c member 2 (SMARCC2) gene were described as underlying Coffin‐Siris syndrome 8 (CCS‐8; MIM: 618362), characterized by ID and multiple malformations." (PMID 41532374, 2026).
developmental delay (3 papers, 2023 to 2025). "De novo variants in the SMARCC2 gene cause intellectual disability and developmental delay and have been associated with ASD." (PMID 36803626, 2023).
glioma (3 papers, 2022 to 2026). A benign or malignant brain and spinal cord tumor that arises from glial cells (astrocytes, oligodendrocytes, ependymal cells). "In this respect, SMARCC2 has been implicated in mediating the Wnt/β-catenin signaling pathway to suppress glioma cell migration and invasion through interaction with C-MYC." (PMID 39349442, 2024). "Next, data from 401 patients with gene mutation information were analyzed, and the mutation rate of SMARCC2 was found to be as high as 20% in gliomas, with loss of heterozygosity (HETLOSS) as a major component." (PMID 36418306, 2022). "Strengthening the credibility of this conclusion, analysis of the survival statistics of 136 patients who underwent postoperative radiotherapy and chemotherapy also indicated that low expression of SMARCC2 was associated with poor prognosis of glioma." (PMID 36418306, 2022). "SWI/SNF-related matrix-associated actin-dependent regulator of chromatin subfamily C member 2 (SMARCC2) negatively regulates Wnt/β-catenin signaling by controlling c-Myc expression, thereby reducing glioma cell invasion and migration." (PMID 41141394, 2026). "This study found that higher-grade gliomas had lower SMARCC2 expression and that higher expression was significantly associated with better prognosis." (PMID 36418306, 2022). "We found that the expression of SMARCC2 was higher in LGG and that the high expression of SMARCC2 tended to characterize a better prognosis of glioma." (PMID 36418306, 2022). "Notably, a previous study reported that SMARCC2 can suppress Wnt/β-catenin signaling, inhibiting glioma cell migration and invasion." (PMID 39349442, 2024). "Low expression of SMARCC2 is found in malignant glioblastoma (GBM) compared with low-grade gliomas." (PMID 36418306, 2022). "Therefore, this study analyzed the difference in SMARCC2 expression between low-grade glioma (LGG) and glioblastoma (GBM) in the TCGA database." (PMID 36418306, 2022). "In addition, in vivo studies confirmed that overexpression of SMARCC2 could significantly inhibit the size of intracranial gliomas in situ in nude mice." (PMID 36418306, 2022).
neuroblastoma (3 papers, 2022 to 2023). Neuroblastoma (NB) is the most common solid, extracranial childhood tumor. "CNBP modulates SWI/SNF activity via SMARCC2 to drive ribosome biogenesis of neuroblastoma cells and subsequent M2 macrophage polarisation." (PMID 37186134, 2023). "Therapeutic targeting of phase separation and interaction of CNBP with SMARCC2 inhibits neuroblastoma progression." (PMID 37186134, 2023).
bladder cancer (2 papers, 2020 to 2022). "The LncMAP analysis determined that LINC00482 formed lncRNA-TF-gene triplet in bladder cancer, among which FOXA1 formed 12 triplets, only secondary to SMARCC2 which formed 19 triplets but it has never been indicated to be associated with bladder cancer." (PMID 33323547, 2020).
Coffin-Siris syndrome 8 (2 papers, 2022). Any Coffin-Siris syndrome in which the cause of the disease is a mutation in the SMARCC2 gene. "Coffin-Siris syndrome-8 (CSS8) is a rare autosomal dominant disorder caused by variants in SMARCC2, a core subunit of the chromatin-remodeling complex BRG1-associated factor (BAF)." (PMID 35241061, 2022). "Haploinsufficiency of SMARCC2 has been associated with Coffin-Siris syndrome 8 (MIM#618362)." (PMID 36303224, 2022).
colorectal cancer (2 papers, 2019 to 2024). A primary or metastatic malignant neoplasm that affects the colon or rectum. "The nuclease benzonase was included in all buffers to minimize post-lysis DNA binding by cGAS, then Co-IP validated interactions between cGAS and SWI/SNF components such as ARID1A, SMARCA4 and SMARCC2 in colorectal cancer cells." (PMID 39080411, 2024). "Human BAF170 (SMARCC2) and BAF155 (SMARCC1), the homologs of Swi3p, are involved in cancers since BAF170 and BAF155 mutations were found in gastric and colorectal cancers and small cell lung cancers, respectively." (PMID 31623074, 2019).
congenital heart disease (2 papers, 2022 to 2025). A heart disease that is present at birth. "We identified three additional patients with congenital heart disease, two of which carried a contiguous gene deletion containing SMARCC2, and one had a de novo SMARCC2 loss-of-function variant." (PMID 35241061, 2022). "Despite evidence that SMARCC2 is essential for cardiac differentiation and driving stage-specific cardiac gene expression programs, none of the individuals with SMARCC2 variants have been associated with congenital heart disease (CHD)." (PMID 35241061, 2022).
lung adenocarcinoma (2 papers, 2021). A carcinoma that arises from the lung and is characterized by the presence of malignant glandular epithelial cells. "For this, we made use of a GR activity score (explained above) and the lung adenocarcinoma dataset from TCGA (91/877 tumours harboured SWI/SNF mutations; SMARCB1 18.09%; SMARCC2 9.52%, SMARCD2 6.66%, SMARCD3 1.90%, ARID1A 29.52%, ARID2 31.42%, SMARCE1 2.85%)." (PMID 34272384, 2021). "Taken together, further research is required on SMARCC1, SMARCC2, and SMARCA5, together with TOP1, as predictive biomarkers of resistance to geldanamycin derivatives as HSP90 inhibitors in lung adenocarcinoma." (PMID 33802597, 2021).
atrophic gastritis (1 paper, 2025). "We also identified several upregulated genes involved in the cell cycle G1/S phase transition in mucous neck cells, including SMARCC2, BCL7C, and CDKN1A, indicating that mucous neck cells acquired an aberrant cell proliferation phenotype in the atrophic gastritis stage." (PMID 39905493, 2025).
autism spectrum disorder (1 paper, 2026). A spectrum of developmental disorders that includes autism, and Asperger syndrome. "SMARCC2 is a chromatin remodeling gene involved in autism spectrum disorder (Ben‐David and Shifman 2013)." (PMID 41532374, 2026).
cervical carcinoma (1 paper, 2022). A carcinoma arising from either the exocervical squamous epithelium or the endocervical glandular epithelium. "To test whether SMARCC1 or SMARCC2 is regulated by SET7, we used siRNA-mediated silencing of SET7 with two representative siRNAs41 and found that loss of SET7 indeed increased the levels of both SMARCC1 and SMARCC2 proteins in human cervical carcinoma HeLa cells." (PMID 36335117, 2022).
epilepsy (1 paper, 2023). A brain disorder characterized by episodes of abnormally increased neuronal discharge resulting in transient episodes of sensory or motor neurological dysfunction, or psychic dysfunction. "Interestingly, among multiple CRF genes, only SMARCA2, SMARCB1, ACTL6B and KDM5C have been previously associated with epilepsy, and some other members of this cluster (e.g., SMARCC1, SMARCC2, SMARCA4 and WRD5) are only cursorily mentioned among epilepsy candidate genes." (PMID 36982355, 2023).
glioblastoma (1 paper, 2022). The most malignant astrocytic tumor (WHO grade IV). "Mutation analysis of the selected glioblastoma patients found that SMARCC2 was mutated in up to 20% of cases." (PMID 36418306, 2022). "In the present study, we demonstrate that the residual SWI/SNF group after SMARCC2 is specifically knocked out leads to the disorder of the genome, and perhaps the development of degraders targeting the residual SWI/SNF complex may be beneficial to SMARCC2-deficient glioblastoma." (PMID 36418306, 2022). "Here, we report that the SMARCC2 subunit of the SWI/SNF chromatin remodeling complex can significantly inhibit the proliferative ability of glioblastoma (GBM) cell lines." (PMID 36418306, 2022). "In this study, we found that SMARCC2 can stabilize the overall structure of SWI/SNF in glioblastoma cell lines." (PMID 36418306, 2022). "In this study, we found a unique function of SMARCC2 in inhibiting the progression of glioblastoma by targeting the DKK1 signaling axis." (PMID 36418306, 2022). "SMARCC2 knockout promoted the proliferation of glioblastoma cells, while its overexpression showed the opposite effect." (PMID 36418306, 2022). "Therefore, this study focuses on the possible molecular mechanism of SMARCC2 in the occurrence and development of glioblastoma." (PMID 36418306, 2022). "Our findings not only suggest that SMARCC2 may serve as a prognostic indicator in glioblastoma patients but also raise the possibility of the clinical benefit of PI3K–AKT inhibition in patients with SMARCC2-low or null cancers." (PMID 36418306, 2022). "Our study showed that SMARCC2 could significantly inhibit the PI3K/AKT pathway in glioblastoma cell lines by targeting DKK1, therefore, targeting DKK1 degraders and PI3K/AKT pathway inhibitors may be a new idea for the clinical treatment of glioblastoma." (PMID 36418306, 2022). "The plate cloning experiment and EdU experiment also confirmed that SMARCC2 could significantly inhibit the proliferation rate of the glioblastoma cell line." (PMID 36418306, 2022). "To better understand SMARCC2, we performed Western blot analysis on six different glioblastoma (GBM) cell lines." (PMID 36418306, 2022). "Overall, this study shows that SMARCC2, as a tumor suppressor, inhibits the proliferation of glioblastoma by targeting the transcription of the oncogene DKK1 through chromatin remodeling, indicating that SMARCC2 is a potentially attractive therapeutic target in glioblastoma." (PMID 36418306, 2022). "Next, we characterized the negative correlation between the expression of DKK1 and SMARCC2 in different glioblastoma cell lines by western blotting." (PMID 36418306, 2022).
hearing loss (1 paper, 2023). "With the advancement of next-generation sequencing genetic screening, mutations in other BAF/PBAF partner genes such as SMARCC2 (BAF170), SMARCG2 (DPF2) and PHF6 have been found in patients affected with CSS-like syndrome affected with hearing loss with varying degree." (PMID 36831199, 2023).
Inguinal hernia (1 paper, 2022). Protrusion of the contents of the abdominal cavity through the inguinal canal. "The grid visualization also highlights the presence of phenotypes in the proband that has predominantly or only been observed in NSD1 probands (e.g., absent/small foot bones) or in SMARCC2 probands (e.g., thick eyebrows, inguinal hernia)." (PMID 36303224, 2022).
lung carcinoma (1 paper, 2022). "The effects of LSD1 silencing are unique for mESCs and F9 cells, as silencing of LSD1 in human embryonic kidney carcinoma 293 T and lung carcinoma H1299 cells that express both SMARCC1 and SMARCC2 did not exhibit any proliferation defects." (PMID 36335117, 2022).
melanoma (1 paper, 2017). A malignant, usually aggressive tumor composed of atypical, neoplastic melanocytes. "The transcripts of 6 significantly changed proteins (VIM, DNM1, SMARCC2, CSDE1, EIF4A2 and ANXA2) have been previously identified as direct RNA targets of CSDE1 in human melanoma cells." (PMID 29129916, 2017).
multiple myeloma (1 paper, 2009). "Three other genes were also down-regulated (SMARCA4, BAZ2A and SMARCC2): SMARCA4 is a drug target candidates in hyperdiploid multiple myeloma; BAZ2A is a novel nucleolar chromatin remodeling machine, and SMARCC2 was among the top discriminating genes in the good prognosis subgroup of MLL." (PMID 19761576, 2009).
Parkinson disease (1 paper, 2024). A progressive degenerative disorder of the central nervous system characterized by loss of dopamine producing neurons in the substantia nigra and the presence of Lewy bodies in the substantia nigra and locus coeruleus. "CHIER also enhanced the visualisation of large SMARCC2+ cytoplasmic bodies, termed cytobodies, which are increased in Parkinson’s Disease (PD)." (PMID 39689145, 2024).
schizophrenia (1 paper, 2021). A major psychotic disorder characterized by abnormalities in the perception or expression of reality. "We also found enrichment of LoF gDNMs in SMARCC2, encoding a component of the SWI/SNF chromatin remodeling complexes, with significance close to the exome-wide threshold in the combined group of BD, schizophrenia, and ASD (P = 5.62 × 10−6, one-tailed Poisson test)." (PMID 34145229, 2021).
squamous cell carcinoma (1 paper, 2020). A carcinoma arising from squamous epithelial cells. "Next, n = 116 samples of patients with pure squamous cell carcinoma (n = 68) and mixed urothelial carcinoma with substantial squamous differentiation (n = 48) were analyzed for seven SWI/SNF complex proteins (ARID1A, SMARCA4, SMARCB1, SMARCC1, SMARCC2, SMARCA2 and PBRM1) by immunohistochemistry." (PMID 33227989, 2020).